MTOR (mechanistic target of rapamycin kinase)
Diseases named in the same sentence as MTOR in open-access papers (continued):
Sharing a sentence is not in itself a finding about the gene and the disease.
tumor (continued). "Through the mammalian target of rapamycin (mTOR), AMPK interferes with cellular growth signaling and inhibits carcinogenesis promotion, tumor cell adhesion, and migration." (PMID 38068717, 2023). "This additional activation of the Pi3K/AKT/mTOR signaling pathway seems to exacerbate the cooperation with BRAF activation and the promotion of tumor cell proliferation." (PMID 36831610, 2023). "The PI3K/AKT/mTOR signaling pathway is abnormally expressed in some common tumors, thereby affecting the EMT process in tumors or promoting tumor metastasis, invasion, and proliferation." (PMID 37415741, 2023). "Top enriched proteins and PTMs in PDX-human tumor pairs include: ERK1, ERK2, ERKpT202, ERKpY204, RAS10, STAT3 Ser727, CrkL Y207, MTOR, PTEN, NFKBp65, S536, FKHR-FOXO2 S256, and PI3Kp85 Y458." (PMID 37280243, 2023). "The coagulants tissue factor (TF) and factor VII (FVII), locally produced in tumor microenvironment, promote HCC growth by the repression of autophagy mediated by mTOR activation and Atg7." (PMID 37189787, 2023). "We also found PDGFRA CNA in the recurrent tumor as well as the xenograft model and upregulated protein expressions in the PI3K/AKT/mTOR pathway and RAS/RAF/MEK/ERK pathway in the recurrent tumor." (PMID 38012788, 2023). "Activation of the mTOR and PI3K pathways can resist tumor cell apoptosis and induce the EMT process." (PMID 36994237, 2023). "In the treatment of several tumor types, fixetine inhibits the PI3K/Akt/mTOR pathway in human NSCLC cells, which can control autophagy." (PMID 37893079, 2023). "For example, lactic acid produced by tumor cells in the hypoxic area is excreted into the stroma through MCT4 and then transported to the oxygen-rich area, where tumor cells uptake lactic acid through MCT1 and activate the mTOR signaling pathway." (PMID 37064872, 2023). "Using the GEPIA2 website, AKT1, MAPK1, and mTOR expression levels were compared between PDAC and a normal population (for tumor tissues, n = 197, and for normal tissues, n = 171)." (PMID 37503215, 2023). "For example, PI3K/mTOR, PI3K/HDAC, PI3K/AKT/mTOR, and PDGFR/PI3K/EGFR/VEGFR2 multi-target inhibitors were developed with the hope of effectively improving anti-tumour activity." (PMID 37489050, 2023). "In breast cancer, miR-491-5p suppresses metastasis through ZNF-703 to regulate AKT/mTOR pathway, suggesting miR-491-5p and ZNF-703 as potential therapeutic targets for this tumor type." (PMID 37369946, 2023). "SFTPC protein levels were downregulated in tumor tissues, whereas PI3K, p-PI3K, AKT, p-AKT, mTOR, p-mTOR, RPS6KB1, and p-RPS6KB1 protein levels were upregulated." (PMID 37955668, 2023). "In this tumor model, 6-shogaol activates AMPK, a positive regulator of autophagy, while inhibiting mTOR, a negative regulator of autophagy." (PMID 37875983, 2023). "On the other hand, PD-L1 activity on the tumor cell surface is reduced, and activation of the intracellular PI3K/AKT/mTOR pathway and inhibition of autophagy are also reduced." (PMID 37006252, 2023). "For example, the activation of the mTOR pathway in tumor cells can induce the secretion of VEGF, which facilitates angiogenesis and tumor growth." (PMID 38075052, 2023). "Then, SRSF1 is able to induce the expression of p-mTOR in order to promote migration, invasion, and EMT in vitro and greater tumor size and lower apoptosis in vivo." (PMID 37047267, 2023). "MTOR signaling pathway, a central signaling pathway controlling tumor metabolism, is one of the signaling pathways that has a fundamental role in the regulation of PI3K/Akt and mTOR signaling pathway function in gastrointestinal cancer." (PMID 37858219, 2023).
tumor (continued). "In prostate cancer, adiponectin inhibits tumor cell growth by suppressing VEGF-A-mediated tumor neovascularization via AMPK/tuberous sclerosis complex 2 (TSC2), resulting in inhibition of mTOR-mediated VEGF-A activation and decreased VEGF-A production." (PMID 37686525, 2023). "The combinatory inhibition of mTOR and VEGF using rapamycin and bevacizumab significantly reduced tumor growth in xenograft models of HCC." (PMID 37631344, 2023). "Consistently, knockdown of REDD1, an inhibitor of mTOR, impedes glycolysis in TAM and inhibits excessive tumor angiogenesis and metastasis." (PMID 37564659, 2023). "PTEN is an upstream regulator of the protein kinase B/mammalian target of rapamycin (AKT/mTOR) signaling pathway, and the AKT/mTOR pathway correlates with tumor proliferation, survival, apoptosis, and invasion/metastasis." (PMID 37733108, 2023). "When the dual PI3K/mTOR inhibitor CCT128930 is applied to OS cells lines (MG63, U2OS, and Saos‐2), cyclin D1 and/or cyclin B1 expression was downregulated in tumor cells, and the cell cycle was stalled at the G0/G1 phase." (PMID 37441462, 2023). "HIFs direct different signaling pathways such as PI3K/Akt/mTOR, NOX, and Wnt/β-Catenin to tumor progression depending on the degree of hypoxia." (PMID 36787054, 2023). "Taken together, these data confirm the key role of mTOR and relevant effectors in the maintenance of stemness and CSC population within the tumour niche." (PMID 37156724, 2023). "Herein, we observed that TBK1 and mTOR inhibitors strongly prevented the TRIM28-induced upregulation of PD-L1 expression and inhibited tumor growth in vivo." (PMID 37357254, 2023). "The PI3K/mTOR/AKT pathway play a significant role in changes of DNA sequences, RNA synthesis, and tumor formation." (PMID 36677808, 2023). "Dysregulation of the Ras-Raf-Mek-ERK, PI3K-Akt-mTOR, PLC- γ 1, signal transducer and activator of transcription, and Src pathways downstream of EGFR are involved in tumor cell proliferation and apoptosis, which are tightly associated with sorafenib resistance." (PMID 36891274, 2023). "In conclusion, PROK1 knockdown significantly prevented tumor growth and promoted apoptosis of human PC cells in vivo, where the PI3K/AKT/mTOR pathway was probably inhibited." (PMID 37070074, 2023). "Collectively, our findings demonstrate that METTL3a is required for mTOR activation at least partially through m6A-mediated suppression of TMEM127 expression, and this modulation contributes to tumor cell proliferation." (PMID 37589705, 2023). "LKB1 is a tumor suppressor that acts by suppressing growth under energetic stress conditions, through its action on the AMPK/mTOR pathway." (PMID 36925926, 2023). "Particularly, emerging evidence has demonstrated that hnRNPA2B1 regulates tumor proliferation and metastasis through the regulation of the AKT/mTOR signaling pathway." (PMID 37990246, 2023). "The tumor samples were used to evaluate the expression of HIF-1α, Nrf2, HO-1, cMyc, cyclin D1, mTOR, and STAT3." (PMID 37465088, 2023). "SCFAs block HIF-1α stimulation of tumor survival and growth under hypoxic conditions, but in immune cells, SCFA stimulation of mTOR signaling regulates T cell fate." (PMID 37432606, 2023). "RHEB, overexpressed in tumor tissues, is a GTP-binding protein positively regulating mTOR activation." (PMID 37444412, 2023). "Attention should be paid to the APOB gene, which is able to impair DNA repair and regulate oncogenic and metastatic regulators (mTOR and PI3K pathways), as well as inhibit tumor suppressors." (PMID 36864816, 2023). "Mechanically, SYNPO2 regulates tumor growth, metastasis, and invasion via activating the PI3K/AKT/mTOR signal and Hippo signaling pathways." (PMID 37544991, 2023). "Down regulation of KIAA0101 suppresses tumor cell progression and glycolysis by inactivating the PI3K/AKT/mTOR pathway." (PMID 36740668, 2023).
tumor (continued). "It has been found that the insulin-like growth factor receptor (IGF-1R)/AKT/mTOR and the mevalonate-isoprenoid biosynthesis pathways were upregulated in CRC stem cells (CSCs), inducing tumor cell growth and proliferation." (PMID 38023258, 2023). "It is known that TRAP1 can overcome metabolic stress and promote tumor cell metastasis by inhibiting the activation of AMPK and then activate mTOR signaling." (PMID 37351538, 2023). "Pathway activity analysis found that three genes were involved in EMT, tumor proliferation, cell cycle cycle, cell damage repair, MAPK and mTOR pathway to varying degrees." (PMID 36650426, 2023). "Studies are warranted given many reports of RHA and JUND dysregulation in neoplasms and the important role we have identified for TGS1 in recovery from mTOR inhibition." (PMID 37386121, 2023). "mTOR and AMPK signaling pathways are the key pathways for regulating immune cell metabolism reprogramming, which in turn affects the tumor immune microenvironment." (PMID 36994237, 2023). "KV suppresses tumor progression via the downregulation of the Erk-RPS6K-TMEM139 and PI3K-Akt-mTOR pathways in oxaliplatin-resistant AsPC-1 cells." (PMID 37174108, 2023). "One study showed dramatic tumor regression in C3-TAg mice following dual treatment of tumor-bearing mice with the drugs AZD6244 (selumetinib) and BEZ235 (dactolisib), resulting in the dual inhibition of PI3K/mTOR and MEK signaling." (PMID 37686596, 2023). "Tumour cells in the TME outcompete T cells for glucose, which leads to sustained mTOR signalling, glycolysis and proliferation, as observed in our female cohort." (PMID 36826068, 2023). "In contrast, iron chelators effectively inhibited mTOR in metastatic TNBC cells and reduced both the size of the primary tumor and lung metastases in a mouse TNBC model." (PMID 36672419, 2023). "Signaling pathways downstream Gas6/AXL signaling, including PI3K/AKT/mTOR, NF-κB, JAK/STAT3 and RAS/RAF/MEK/ERK, play critical roles in tumor cell cycle regulation, malignancy and drug resistance." (PMID 37265798, 2023). "MET is activated by auto-phosphorylation when bound by HGF engaging several downstream signaling networks, including the PI3K/AKT/mTOR, phospholipase C (PLC), and RAS/MAPK/RAF/ERK pathways involved in tumor growth and invasion." (PMID 36831657, 2023). "MiR-520a-3p is a gene with tumor-suppressive effects in numerous distinct solid tumors, and there is evidence that inhibit NSCLC growth by inactivating the PI3K/AKT/mTOR signaling pathway." (PMID 38169723, 2023). "We found that let‐7c‐3p regulates the PI3K/AKT/mTOR signaling pathway by inhibiting the expression of PIK3CA, exerting an anti‐tumor effect." (PMID 36412203, 2023). "The PI3K/Akt/mTOR signaling pathway regulates the synthesis and stabilization of HIF-1α in hypoxic tumor cells." (PMID 37227584, 2023). "GB-derived EVs also promote proliferation and migration of neuronal progenitor cells through the PI3K-Akt-mTOR pathway and can potentially participate in transformation of these stem-like cells, such that they become tumor-like and may participate in support of tumor recurrence." (PMID 38074665, 2023). "Ferroptosis can be activated or resisted through different signaling pathways to regulate tumor growth and drug resistance, such as hippo signaling pathway, PI3K/AKT/mTOR signaling pathway and so on." (PMID 37313458, 2023). "After polarization, M2 macrophages secreted abundant CCL8 and accelerated tumor progression and metastasis through the CCR5/mTOR pathway." (PMID 38136340, 2023). "MYC regulates tumor proliferation, metastasis, and metabolism through signaling pathways such as the AKT/mTOR pathway." (PMID 37122373, 2023). "In light of these details, and the well supported role of AKT/mTOR in regard to EMT in ccRCC, increased scrutiny of Jade-1 as a tumor suppressor of ccRCC and a potential agent inhibiting the EMT phenotype is much needed." (PMID 37175531, 2023).
tumor (continued). "For instance, it has been recently stated that inhibiting the mTOR pathway significantly stimulates antitumor immune response via increasing the frequency of long-lived CD8+ memory T cells and improving tumor cell eradication." (PMID 37046703, 2023). "Western blotting results from tumor xenograft samples showed PTEN expression level was decreased and p-AKT and mTOR expression was significantly increased in tumors induced by HOXC10 overexpression." (PMID 37733108, 2023). "Tumor growth and treatment resistance are both influenced by the activation of the PI3K/AKT/mTOR pathway." (PMID 37446814, 2023). "In summary, we report that PTPRH promotes glycolysis, proliferation, migration, and invasion via the PI3K/AKT/mTOR signaling pathway in NSCLC and ultimately promotes tumor progression, which can be regulated by LY294002 and 740Y-P." (PMID 37974250, 2023). "Lipid accumulation can aggravate tumor progression via AMP-kinase and mTOR signaling, and TG plays an irreplaceable role in this pathway." (PMID 37553571, 2023). "In summary, this research identified NMT1 as a tumor promoter in GC and revealed that SPI1 mediated NMT1 to facilitate GC cell viability, migration, and invasion by activating the PI3K/AKT/mTOR pathway." (PMID 36967718, 2023). "One study has found that PI3K/AKT/mTOR axis is highly activated in HNSCC, which is related to the proliferation, migration, invasion, and other biological behaviors of tumor cells." (PMID 37547764, 2023). "Enrichment analysis of hallmark gene sets suggested that the upregulated genes in ESCC tumor were enriched in multiple metabolic related pathways, such as xenobiotic, bile acid and heme metabolism pathways, as well as PI3K/Akt/mTOR pathways." (PMID 36850011, 2023). "LncRNA CASC9 can promote tumor proliferation by inhibiting autosis and autophagy-mediated apoptosis through AKT/mTOR pathway in oral squamous cell carcinoma." (PMID 37313458, 2023). "It was observed that HOXD8 overexpression diminishes the phosphorylation of AKT and mTOR, which further inactivates the AKT/mTOR signaling pathway and decreases tumor growth and proliferation." (PMID 37174125, 2023). "The crosstalk between the Akt/mTOR and MAPK/MEK/ERK pathways that drive tumor growth and cell spread is well known." (PMID 37190229, 2023). "ONC201 also exerted cytotoxicity and apoptosis effects on HCT116 cells, and these anti-tumor effects appeared to be acted through the regulation of TRAIL/DR-5L and mTOR expression in CRC cells." (PMID 36511604, 2023). "Inhibition of PI3K/AKT/mTOR signaling by miR-99a reduced cell invasion of EC, and MK2206, an allosteric AKT inhibitor, decreased tumor growth and invasion in patient-derived xenografts of EC." (PMID 36773034, 2023). "The signaling via mechanistic target of rapamycin (mTOR), such as PI3K-AKT-mTOR, which makes NF-κB an important endogenous tumor promoter is involved in tumor proliferation and survival." (PMID 38273841, 2023). "Numerous signaling pathways are involved in tumor resistance, including PI3K‐Akt–mTOR and TGF‐β signaling pathways." (PMID 35635121, 2023). "In fact, our data highlight the benefits of mTOR inhibition during early CD8 T cell differentiation by rescuing the terminal differentiation of lin28Tg CTLs in vitro, and enhancing tumor rejection in vivo." (PMID 37696797, 2023). "In conclusion, BV, as the tumor-stimulating metabolite of Efa, generates proliferative and angiogenic effects on CRC, which is mainly mediated by the activation of PI3K/AKT/mTOR." (PMID 36732757, 2023). "Astragalus saponins can inhibit tumor angiogenesis by regulating mTOR signalling and decreasing the level of VEGF protein expression in tumor cells." (PMID 37876967, 2023). "Our group studied the expression of mTOR and EGFR in LSCC cells and their correlation with tumor neo-angiogenesis, in terms of CD105-assessed MVD, and prognosis." (PMID 37445908, 2023).
tumor (continued). "Multi-label immunohistochemistry (IHC) showed that tumor tissues injected with ASO exhibited fewer HNRNPLL, phospho-AKT, and phospho-mTOR positive cells." (PMID 37461053, 2023). "The three Hub TF genes are highly upregulated in TNBC and affect the proliferation of tumor cells through the PI3K-Akt signaling pathway, Wnt signaling pathway, FOXO signaling pathway, and mTOR signaling pathway, resulting in a poor prognosis." (PMID 37686305, 2023). "Angiogenic factors are controlled by hypoxia-inducible factors (HIFs), the mechanistic target of rapamycin (mTOR), and the unfolded protein response (UPR): they both provide immunomodulatory and vascular actions in the tumor microenvironment." (PMID 36976529, 2023). "As for drug sensitivity, the low-risk group was more sensitive to six inhibitors of the PI3K/AKT/mTOR pathway, such as rapamycin, which not only enhanced immunotherapeutic effects but also blocked SASP-induced tumor progression." (PMID 37303739, 2023). "Incorporation of a PI3K/AKT/mTOR inhibitor functions synergistically with endocrine therapy and CDK4/6 inhibitors to inhibit tumor growth and prevent or overcome resistance to standard therapy in ER+ metastatic breast cancer." (PMID 36901954, 2023). "Several major signaling pathways have been identified in OS tumor development and metastasis, including the PIK3, JAK/STAT, Wnt/β-catenin, NOTCH, Hedgehog, Ras, TGF-β, MAPK/AKT/mTOR, RANK/RANKL, and NF-κB signaling pathways." (PMID 37511127, 2023). "The LIF receptor complex, composed of LIF, LIFR, and glycoprotein 130 (gp130), is responsible for promoting tumor growth, progression, and metastasis through the direct effect of JAK/STAT3 and other downstream pathways, such as MAPK, AKT, and mTOR." (PMID 37103052, 2023). "According to research findings, autophagy in TAMs was found to decrease the proportion of tumor‐promoting macrophages via the ROS/ERK and mTOR signaling pathways." (PMID 36794651, 2023). "The fidelity of the anti-tumor response in the PDX and xenoline models was systemically evaluated using the MEK inhibitor trametinib and mTOR inhibitor Everolimus, both of which were previously used in the patient." (PMID 37280243, 2023). "One study showed that a low-dose triple drug combination targeting the PI3K/AKT/mTOR pathway and the MAPK pathway significantly reduced tumor growth in two patient-derived xenograft (PDX) models." (PMID 37270486, 2023). "It is worth noting that FOXA1 target genes were mainly enriched in pathways related to apoptosis, mitosis, mTOR, TNF-α, indicating its possible involvement in tumor malignant proliferation and supporting our fold enrichment of CERES scores above." (PMID 37876590, 2023). "The next biological pathways most significantly enriched were the TRAIL signalling pathway, involved in apoptosis cascades (3.166‐fold enrichment), and the mTOR signalling pathway, the known intracellular driver of TSC tumours (2.990‐fold enrichment)." (PMID 37337371, 2023). "The PI3K/AKT/mTOR pathway is activated, whereas the ERK1/2 MAPK pathway is inactivated in different types of tumor tissues." (PMID 37953768, 2023). "For example, insulin and IGF-I activate PI3K/Akt/mTOR and Ras/Raf/MAPK signaling pathways, thereby stimulating tumor growth." (PMID 37954072, 2023). "We found that exposure to morphine results in tumor cell proliferation and migration, accompanied by phosphorylation of AKT and S6, indicating the activation of the PI3K/AKT/mTOR signaling pathway." (PMID 36835812, 2023). "Various clinical trial studies have shown that lenvatinib combined with everolimus can exhibit antiangiogenic and anti-tumor effects by suppressing VEGFR, FGFR, and mTOR signaling pathways." (PMID 36703202, 2023). "Based on the important role of the PI3K/Akt/mTOR signaling pathway in cell metabolism, survival, proliferation, and tumor progression, the gene expressions of PI3K, AKT, and mTOR were determined by RT-PCR in the colon tissues." (PMID 37493814, 2023).